MIR518B (microRNA 518b)
Synonyms: hsa-mir-518b; MIRN518B; mir-518b
Gene: MicroRNA gene on chromosome 19 (53,702,737 to 53,702,819, forward strand). Ensembl gene ENSG00000207862.
Gene Ontology:
Biological process: miRNA-mediated post-transcriptional gene silencing
Homologues: Orthologues: chimpanzee ptr-mir-518b (100% identical). Paralogues in human: MIR518C (89% identical), MIR518D (89% identical), MIR523 (89% identical), MIR519B (88% identical), MIR518E (87% identical), MIR518F (87% identical), MIR520C (87% identical), MIR522 (87% identical), MIR516A1 (86% identical), MIR519C (86% identical), MIR516A2 (84% identical), MIR519A2 (84% identical), and 12 more.
Diseases named in the same sentence as MIR518B in open-access papers:
MIR518B is named in the same sentence as 2 diseases in open-access papers, as found by Europe PMC text mining. Sharing a sentence is not in itself a finding about the gene and the disease. The quoted sentences say what the papers report.
glioblastoma (1 paper, 2021). The most malignant astrocytic tumor (WHO grade IV). "At the same time, MIR518B was up-regulated and reported to manifest tumor suppressive properties in glioblastoma." (PMID 34204289, 2021).
MIR518B also shares sentences with these, for which no sentence is quoted: tumor (1 paper).